KIF11 (kinesin family member 11)
Diseases named in the same sentence as KIF11 in open-access papers (continued):
Sharing a sentence is not in itself a finding about the gene and the disease.
retinopathy (7 papers, 2016 to 2025). "From this analysis, it was possible to conclude that chorioretinal dysplasia is the dominant phenotype in KIF11-associated retinopathy, while ISPV is common in FEVR with mutations in other genes." (PMID 38939361, 2024). "They stated that chorioretinal dysplasia was the principal retinal feature in KIF11-associated retinopathy." (PMID 36672954, 2023). "Taken together, these findings indicate that most KIF11 variants cause KIF11-associated retinopathy through a loss of function mechanism." (PMID 36672954, 2023). "Our results further verified that the loss of KIF11 function was a mechanism underlying KIF11-related retinopathy." (PMID 36672954, 2023). "Chorioretinal dysplasia, instead of retinal folds, was the dominant phenotype in KIF11-associated retinopathy." (PMID 35456519, 2022). "The current study is in line with previously published reports on MCLMR, which demonstrated that choroidopathy is the dominant phenotype in KIF11-associated retinopathy; this differs from FEVR unrelated to KIF11." (PMID 35456519, 2022). "Increase and straightening of peripheral vessels (ISPV) was observed in 17.1% (12/70) of eyes with KIF11-associated retinopathy, and in 50% (39/78) of eyes with FEVR with mutations in other genes (p < 0.01)." (PMID 35456519, 2022). "Recently, it has been proposed that KIF11-associated retinopathy varies with FEVR, and several cases have been reported to verify this suggestion." (PMID 35456519, 2022). "The manifestation of KIF11-associated retinopathy was variable and different from the phenotype in FEVR caused by other genes." (PMID 35456519, 2022). "Compared with FEVR with disease-causing mutations in other genes, chorioretinal dysplasia was observed in 44.2% (31/70) of eyes with KIF11-associated retinopathy and in only 1.3% (1/70) of eyes with FEVR with mutations in other genes (p < 0.01)." (PMID 35456519, 2022). "Therefore, the term KIF11-associated retinopathy has been proposed to refer these disorders by genotype rather than phenotype." (PMID 36672954, 2023). "Therefore, we suggest that choroidopathy or chorioretinal dysplasia, not retinal folds or abnormal vessels, is the dominant ocular phenotype in KIF11-associated retinopathy." (PMID 35456519, 2022). "We suggest that ISPV is an ocular feature that can help distinguish KIF11-associated retinopathy from FEVR caused by other variants, but it is only useful in patients whose retina could be observed." (PMID 35456519, 2022). "In this study, we performed a full genetic analyses and reported the clinical findings in a Chinese cohort with KIF11-related retinopathy from a tertiary center." (PMID 36672954, 2023). "The key retinal features for KIF11-related retinopathy were retinal folds, tractional retinal detachment, and chorioretinal dysplasia." (PMID 36672954, 2023). "The patients displayed a variable phenotype expressivity and incomplete penetrance, indicating the importance of genetic analysis for patients with KIF11-related retinopathy." (PMID 36672954, 2023). "The purpose of this study was to detect the missing heritability of patients with KIF11-related retinopathy and to describe their clinical and genetic characteristics." (PMID 36672954, 2023). "This indicates that chorioretinal dysplasia is the critical difference between KIF11-associated retinopathy and FEVR unrelated to KIF11." (PMID 35456519, 2022). "In this study, ISPV was observed in 12 eyes with KIF11-associated retinopathy, which was noted in 39 eyes with FEVR unrelated to KIF11." (PMID 35456519, 2022). "DIV explained rare unresolved cases with KIF11-related retinopathy." (PMID 36672954, 2023). "The DIVs elucidated the rare unsolved Chinese cases with KIF11-related retinopathy." (PMID 36672954, 2023).
retinopathy (continued). "In our cohort studies, chorioretinal dysplasia was seen in 31 (44.2%) eyes in KIF11-associated retinopathy and in one (1.3%) eye in FEVR unrelated to KIF11, while retinal folds were noted in 24 (34.3%) eyes in KIF11-associated retinopathy and 30 (38.5%) eyes in FEVR unrelated to KIF11." (PMID 35456519, 2022). "Whether KIF11-related ocular anomalies belong to the clinical spectrum of FEVR-related retinopathy or whether they are part of a single MCLMR entity remains controversial." (PMID 35456519, 2022). "At present, however, no discernible genotype–phenotype correlation has been established in KIF11-associated retinopathy, as some variant carriers show mild effects or no clinical features, suggesting incomplete penetrance and variable expressivity for the phenotype." (PMID 36672954, 2023).
infection (4 papers, 2022 to 2025). The state of being infected such as from the introduction of a foreign agent such as serum, vaccine, antigenic substance or organism. "Upregulation of many genes associated with activation of innate immunity and SARS CoV-2 disease severity were identified during acute (4 dpi) SARS-CoV-2 (Delta variant) infection in cats, such as KIF11, IRF7, OAS1, BATF2, IF16, and BPIFA1." (PMID 35746678, 2022). "In support of this, we also demonstrate that Kif11, along with other mitotic kinesins, are in proximity to the L2 protein during infection." (PMID 39629998, 2025). "First, we overexpressed 3×Flag-TACC3 in Panc-1 cells via lentiviral infection and measured the expression level of KIF11 by Western blotting." (PMID 38012214, 2023). "In addition, Kif11, along with kinesins Kif18a and Kif25, were in proximity to L2 during infection." (PMID 39629998, 2025). "We next utilized PLA to determine that several mitotic kinesins, including Kif11, are in close proximity with the L2 protein of HPV16 during infection in both interphase and mitotic cells." (PMID 39629998, 2025). "Furthermore, seven genes (CDK1, TYMS, MCM5, KIF11, CCNB2, MAD2L1, and MCM4) have been identified as core hub genes involved in cell-cycle regulation, potentially serving as mediators in the pathogenesis triggered by NN1172 infection within the thymus." (PMID 38362295, 2024). "In lieu of not being able to show a direct interaction between Kif11 and L2 via CoIP, we utilized proximity-ligation assays (PLAs) to determine if Kif11 and HPV16L2 are in close proximity during infection, as used previously in HPV16 entry studies." (PMID 39629998, 2025).
peripheral neuropathy (4 papers, 2017 to 2022). A disorder affecting the peripheral nervous system. "Some of these MAPs, like Kinesin Spindle Protein (KSP), also known as KIF11 or Kinesin Eg5, are not expressed in terminally differentiated cells, such as neurons; therefore, toxicities such as peripheral neuropathy are not predictable with KIF11 inhibitors." (PMID 34548908, 2021).
autosomal dominant disease (1 paper, 2022). Autosomal dominant form of disease. "Most interestingly there is a variation of unknown significance in KIF11, defects in which can cause autosomal dominant disease." (PMID 34977425, 2022).
gastrointestinal tumors (1 paper, 2021). "PBK, AURKB, KIF11, and PLK1 confirmed that they are closely related to the occurrence and progression of gastrointestinal tumors, including HCC." (PMID 34200261, 2021).
neurodevelopmental disorder (1 paper, 2024). A behavioral and cognitive disorder with onset during the developmental period that involves impaired or aberrant development of intellectual, motor, or social functions. "We designed a parent support group survey that showed a higher prevalence of neurodevelopmental disorders in children with KIF11 mutations compared to the general population." (PMID 39359715, 2024). "In this case report, we present the profile of a boy affected by KIF11-associated disorder, alongside these two additional neurodevelopmental disorders: ADHD and ASD." (PMID 39359715, 2024). "Furthermore, a better understanding of the increased prevalence of ASD and ADHD in individuals with KIF11 mutations could provide valuable insights into the genetic pathogenesis of neurodevelopmental disorders." (PMID 39359715, 2024). "Moreover, gaining a deeper understanding of the higher prevalence of ASD and ADHD in individuals with KIF11 mutations could offer valuable insights into the genetic mechanisms underlying neurodevelopmental disorders." (PMID 39359715, 2024). "We advise early referral to child psychiatry for interventions with the purpose of improving quality of life for the patient and his family, as individuals with KIF11 cases may exhibit a higher prevalence of these neurodevelopmental disorders compared to the general population." (PMID 39359715, 2024). "Despite the relatively small size of our group, the data strongly suggest a higher prevalence of neurodevelopmental disorders, ASD, and ADHD in the KIF11 group compared to the general population." (PMID 39359715, 2024).
KIF11 also shares sentences with these, for which no sentence is quoted: breast tumor (5 papers); neuroblastoma (5); Autosomal dominant microcephaly (4); chronic myelogenous leukemia (4); gastric adenocarcinoma (4); microphthalmia (4); developmental delay (3); esophageal squamous cell carcinoma (3); head and neck squamous cell carcinoma (3); non-small cell lung carcinoma (3); pancreatic ductal adenocarcinoma (3); renal carcinoma (3); renal cell carcinoma (3); acute lymphoblastic leukaemia (2); breast adenocarcinoma (2); ciliopathies (2); esophageal cancer (2); kidney cancer (2); microcephaly-lymphedema-chorioretinal dysplasia (2); myopia (2); Nystagmus (2); osteosarcoma (2); primary lymphedema (2); Usher syndrome (2); acquired immune deficiency syndrome (1); acute myocardial infarction (1); adenocarcinoma (1); adrenocortical carcinoma (1); Aicardi syndrome (1); albinism (1).
A further 71 diseases each share a sentence with KIF11 in 1 paper.